RAET1E (retinoic acid early transcript 1E)
Description:
Binds and activates the KLRK1/NKG2D receptor, mediating natural killer cell cytotoxicity.
Synonyms: N2DL-4; NKG2DL4; LETAL; ULBP4; bA350J20.7; RAET1E2; RL-4
Tractability: Antibody: its Gene Ontology location is reachable by antibodies, with high confidence; UniProt places it where antibodies can reach, with medium confidence; UniProt predicts a signal peptide or a membrane-spanning region.
Gene: Protein-coding gene on chromosome 6 (149,883,179 to 149,898,113, reverse strand). Ensembl gene ENSG00000164520.
Subcellular location: Membrane; Secreted (Isoform 4)
Subcellular location (Human Protein Atlas): Focal adhesion sites; Cytosol
Pathways (Reactome):
Immune System: Immunoregulatory interactions between a Lymphoid and a non-Lymphoid cell
Gene Ontology:
Molecular function: natural killer cell lectin-like receptor binding; protein binding; receptor ligand activity
Biological process: natural killer cell mediated cytotoxicity; positive regulation of natural killer cell mediated cytotoxicity; antigen processing and presentation of endogenous peptide antigen via MHC class I via ER pathway, TAP-independent; antigen processing and presentation of endogenous peptide antigen via MHC class Ib; positive regulation of T cell mediated cytotoxicity; signal transduction
Cellular component: cytosol; focal adhesion; membrane; external side of plasma membrane; plasma membrane; extracellular region
Genetic constraint (gnomAD): Loss-of-function variants: 24 observed, 20.9 expected, observed/expected ratio (o/e) 1.15, 90% interval 0.83 to 1.61. The upper end of that interval is the gene's LOEUF score, 1.61, which puts it in group 6 of 6, group 1 being the genes least tolerant of losing a copy. Missense variants: 283 observed, 300.19 expected, observed/expected ratio (o/e) 0.94, 90% interval 0.86 to 1.04. Synonymous variants: 100 observed, 109.5 expected, observed/expected ratio (o/e) 0.91, 90% interval 0.78 to 1.08.
Homologues: Orthologues: chimpanzee RAET1E (97% identical), macaque RAET1E (83% identical), rat LOC120097698 (26% identical), rat Raet1ll1 (26% identical), rat AABR07000147.1 (25% identical), rat Raet1e (25% identical), rat H60al (24% identical), rat LOC120098769 (22% identical), mouse Raet1d (22% identical), mouse Raet1e (22% identical), rat AABR07000137.1 (22% identical), rat H60bl1 (20% identical), and 10 more. Paralogues in human: ULBP1 (35% identical), ULBP3 (34% identical), ULBP2 (30% identical), RAET1L (30% identical), RAET1G (29% identical), HLA-E (22% identical), HLA-A (21% identical), HLA-B (21% identical), HLA-F (21% identical), HLA-G (21% identical), HLA-C (21% identical), AZGP1 (20% identical), and 10 more.
Diseases named in the same sentence as RAET1E in open-access papers:
RAET1E is named in the same sentence as 35 diseases in open-access papers, as found by Europe PMC text mining. Sharing a sentence is not in itself a finding about the gene and the disease. The quoted sentences say what the papers report.
cervical carcinoma (6 papers, 2014 to 2022). A carcinoma arising from either the exocervical squamous epithelium or the endocervical glandular epithelium. "Overall, the expression of several NKG2DLs, namely MICA/B, ULBP1, and RAET1E, were increased in cervical cancer patients." (PMID 25510288, 2014). "MICA/B, ULBP1, and RAET1E expression was higher in cervical cancer than in low-grade CIN (p < 0.001, p = 0.012, p = 0.013, respectively) and normal cervix (all p < 0.001)." (PMID 25510288, 2014). "For immunostimulator, SLC30A10 expression was correlated with TNFRSF25 (Spearman: ρ = 0.202, P = 0.00038), TNFSF13 (Spearman: ρ = -0.193, P = 0.000703), TNFRSF13C (Spearman: ρ = -0.209, P = 0.000245), and RAET1E (Spearman: ρ = 0.197, P = 0.000546) in cervical carcinoma." (PMID 35154468, 2022). "This trend of progressively increasing MICA/B, ULBP1, and RAET1E expression corresponded to the phases of cervical cancer progression and was significant according to Spearman’s rank correlation (ρ-value of 0.313 [p < 0.001], 0.285 [p < 0.001], or 0.136 [p < 0.001], respectively)." (PMID 25510288, 2014).
breast carcinoma (4 papers, 2015 to 2024). "We also identified some category 2 genes such as ARL6IP5, RAET1E, and ANO7 that could be crucial for breast cancer development and prognosis." (PMID 25803781, 2015). "We also identified some genes such as ARL6IP5, RAET1E, and ANO7 that could be crucial for breast cancer development and prognosis." (PMID 25803781, 2015).
ovarian carcinoma (4 papers, 2012 to 2023). A malignant neoplasm originating from the surface ovarian epithelium. "Similarly, worsened prognosis of ovarian cancer has been linked to the expression of ULBP1, ULBP3 or RAET1E (ULBP4) in univariate analysis and RAET1E (ULBP4), RAET1G (ULBP5) and ULBP2 in multivariate analysis." (PMID 37626965, 2023).
liver cancer (3 papers, 2018 to 2022). An epithelial or non-epithelial malignant neoplasm that arises from the liver. "Six genes (BIRC5, CACYBP, NR0B1, RAET1E, SPINK5, SPP1) were up-regulated in the liver cancer tissues compared to the normal tissues in the TCGA HCC dataset, and S100A8 was downregulated." (PMID 33568167, 2021).
nasopharyngeal carcinoma (3 papers, 2017 to 2024). A carcinoma arising from the nasopharyngeal epithelium. "RAET1E (also known as ULBP4) is a protein-coding gene involved in the immune response, which was previously associated with poor prognosis in ovarian, bladder, and nasopharyngeal cancers." (PMID 38612473, 2024).
atherosclerosis (1 paper, 2018). A disease characterized by the build-up of fatty material and calcium deposition in the arterial wall resulting in partial or complete occlusion of the arterial lumen. "In an animal model, new evidence has been reported supporting the role of raet1e as an atherosclerosis-associated gene." (PMID 30662365, 2018). "In the mouse model, the lack of aortic expression of the raet1e gene results in increased atherosclerosis." (PMID 30662365, 2018).
coronary artery disease (1 paper, 2018). "Our objective was to establish if raet1e polymorphisms are associated with the risk of developing premature coronary artery disease (CAD) or with the presence of cardiometabolic parameters." (PMID 30662365, 2018).
hepatocellular carcinoma (1 paper, 2021). A malignant tumor that arises from hepatocytes. "BIRC5, SPINK5, SPP1, CACYBP, RAET1E, and NR0B1 were significantly up-regulated, and S100A8 was significantly down-regulated in hepatocellular carcinoma samples based on TCGA-HCC dataset." (PMID 33568167, 2021).
pancreatic cancers (1 paper, 2023). "In ovarian, head and neck, and pancreatic cancers, the expression of NKR ligands B7-H6, ULBP2, RAET1E, and death receptor TRAIL-R were associated with a poorer prognosis." (PMID 36839682, 2023).
pneumococcal meningitis (1 paper, 2016). An acute purulent infection of the meninges and subarachnoid space caused by Streptococcus pneumoniae, most prevalent in children and adults over the age of 60. "In the first genome wide association study on outcome in pneumococcal meningitis gene variants in AKT3, DCTN4 and RAET1E were associated with unfavourable outcome in adults with pneumococcal meningitis." (PMID 27193124, 2016). "In conclusion, we identified gene variants in AKT3, DCTN4 and RAET1E to be associated with unfavourable outcome in adults with pneumococcal meningitis." (PMID 27193124, 2016). "To explore the role of AKT3, DCTN4, and RAET1E during pneumococcal meningitis we determined their brain expression levels in our mouse model." (PMID 27193124, 2016).
tumor (17 papers, 2012 to 2025). "In cervical cancer, improved prognosis was linked to the expression of MICA/B and ULBP1, whereas reduced survival (univariate analysis only) was seen when tumours were RAET1E (ULBP4)- or RAET1G (ULBP5)-positive." (PMID 37626965, 2023). "RAET1E belongs to a ligand family for NKG2D in humans and can produce a soluble, 35-kDa protein (named RAET1E2) in tumor cells." (PMID 33568167, 2021). "Furthermore, γδ T cells can recognize and target tumor cells that express a wide range of stress-induced ligands or antigens associated with malignancy including, for instance, MICA, MICB, and LETAL/RAET1E." (PMID 38541651, 2024). "Global gene expression analysis of BVE-Ctnnb1null tumor cells showed up-regulation of NKG2D receptor activating ligands (H60a, H60b, H60c, Raet1a, Raet1b, Raet1c, Raet1d, Raet1e, and Ulbp1) and down-regulation of inhibitory MHC class I molecules H-2L and H-2K2 in BVE-Ctnnb1null tumor cells." (PMID 37483610, 2023). "BVE-Ctnnb1null cells showed up-regulation of NKG2D activating ligands (H60a, H60b, H60c, Raet1a, Raet1b, Raet1c, Raet1d, Raet1e and Ulbp1) and down-regulation of inhibitory MHC class I molecules (H2-L, H2-K2, and H2-D1), which may lead to NK cell activation and tumor cell clearance." (PMID 37483610, 2023).
cancer (6 papers, 2017 to 2025). A tumor composed of atypical neoplastic, often pleomorphic cells that invade other tissues. "In the IHC data of HPA, there is a lack of carcinoma or corresponding normal tissues of several candidate genes includingSDR9C7,RDH12,RAET1E,CERS3,PLA2G4E,CYP4F22, andDENND2C." (PMID 36017889, 2022).
RAET1E also shares sentences with these, for which no sentence is quoted: glioma (4 papers); infection (3); malignant glioma (3); adenocarcinoma (1); asthma (1); B-cell chronic lymphocytic leukemia (1); breast tumor (1); cervical intraepithelial neoplasia (1); colorectal cancer (1); experimental autoimmune encephalomyelitis (1); glioblastoma (1); lung adenocarcinoma (1); lung squamous cell carcinoma (1); lymph node metastasis (1); lymphoma (1); mastocytoma (1); melanoma (1); multiple myeloma (1); multiple sclerosis (1); myopia (1); sarcoma (1); squamous cell carcinoma (1); thymoma (1).